IL6 (interleukin 6)
Diseases named in the same sentence as IL6 in open-access papers (continued):
Sharing a sentence is not in itself a finding about the gene and the disease.
COVID-19 (continued). "We found that the median concentration of IL-6 in COVID-19 patients (72.0 [IQR, 8.5-80.9] pg/mL) exceeded the reference value." (PMID 34123873, 2021). "We also found that heavily infected secretory cells expressed abundant IL-6, a potential mediator of COVID-19 pathogenesis." (PMID 33507952, 2021). "A recent study demonstrated that COVID-19 severe patients had a low level of counts of T cells and a high level of IL-2, IL-6, IFN-γ, and IL-10 compared with the mild patients, similar to the results in SARS and MERS." (PMID 33833618, 2021). "As targeting IL-6 is a potential therapeutic strategy for COVID-19 (Y and R, 2021), our results showed that IL-6 targeted replicase-transcriptase complex (Nsp13), accessory factor (ORF8) and structural protein (E)." (PMID 36303774, 2021). "We found moderate evidence for the role of IL-6 signalling in COVID-19 in agreement with a previous report." (PMID 34402426, 2021). "During COVID-19, pro-inflammatory cytokines such as interferon, interleukins (IL-6, IL-12, IL-7), and chemokines (CXCL10 and CCL2) are essential to rule clinical complications." (PMID 34603282, 2021). "An attempt to correlate serum cytokine concentrations for over 1500 COVID-19 hospitalized patients with disease outcomes revealed that levels of IL-6, IL-8, and TNF correlated with disease outcome and mortality." (PMID 33445583, 2021). "In both moderate and severe COVID-19 patients, the average concentrations of IL-4, IL-6, IL-10, CCL2, IFN-γ, and TNF-α (P<0.05) were higher than those in healthy donors." (PMID 34489974, 2021). "TNF and IL6 were previously shown to be among the master cytokines involved in COVID-19 related hyperinflammation." (PMID 34088975, 2021). "In particular, we investigated its ability to bind to IFNγ and IL-6 cytokines and inhibit their signalling pathways that allows for modulation of the development of a cytokine storm, including in patients with acute COVID-19." (PMID 34639073, 2021). "Many COVID-19 investigations focus on IL-6, claiming it is the prime suspect for inducing the proinflammatory response within the body and correlating it positively with the severity of COVID-19 symptoms." (PMID 33467912, 2021). "There was a significant correlation between the decrease of interleukin-6 level and the improvement of olfaction and taste function in COVID-19 patients." (PMID 34425827, 2021). "A recent study has shown a significant elevation of IL-6 in some COVID-19 patients, especially in critically ill patients." (PMID 34428204, 2021). "Here, we reviewed the levels of interleukin-6 (IL-6), coagulation indexes, and clinical manifestations of a patient with severe COVID-19 after Tocilizumab administration." (PMID 34485700, 2021). "Hyperviscosity is not only caused by increases in fibrinogen level, but also by the cytokine storm, which plays an important role in increasing viscosity levels in those with COVID-19 by inducing the excessive release of IL-6 and TNF-α114,115." (PMID 33708378, 2021). "PIMS-TS children had significantly elevated levels of cytokines, IFNγ, IL-2, TNFα, IL-1α, IFNα, IFNβ, IL-6, IL-17A, GM-CSF, IL-10, IL-33 and IL-Ra in comparison to COVID-19, seropositive and control children." (PMID 33813138, 2021). "Some investigations have detected much higher IL-6 and IL-10 levels in patients with critical COVID-19 than in those with severe COVID-19." (PMID 34829906, 2021). "IL-6 is significantly higher on admission in COVID-19 patients who eventually experience severe or critical illness than in those with mild or moderate disease." (PMID 34567235, 2021). "The limited data suggests that COVID-19 pregnancies have similar elevations of cytokines (IL-6, TNFα) and chemokines (CCL2, CXCL10) as other COVID-19 patients." (PMID 33168125, 2021). "Another point of overlap is IL-6, which was shown to be elevated in COVID-19 and was also considered a biomarker with prognostic value in AD." (PMID 34942956, 2021).
COVID-19 (continued). "In the subsequent hyper-inflammatory phase, severe COVID-19 cases dramatically increase the levels of IL-2, IL-6, IL-7, IL-10, IP-10, CCL2 (also known as monocyte chemoattractant protein-1/MCP1), TNF-α, macrophage inflammatory protein-1α (MIP1α), and G-CSF." (PMID 34946266, 2021). "Overall, patients with severe COVID-19 present with lymphopenia, and are likely to have increased inflammatory cytokines such as IL-6, granulocyte-macrophage colony-stimulating factor (GM-CSF), and granulocyte colony-stimulating factor (G-CSF)." (PMID 34260666, 2021). "A number of studies have reported that increased levels of inflammatory mediators such as CRP, IL-6, procalcitonin, and serum ferritin were commonly seen among patients with COVID-19, especially in critical or death cases." (PMID 33859687, 2021). "As an indication of inflammation, a large amount of IL-6 was found in patients' blood with extreme symptoms of COVID-19." (PMID 34054974, 2021). "A recent study showed that both obesity and a lower number of CD8+ T cells predict a more severe course of the disease and that CD8+ T cell counts are negatively correlated with IL-6 levels in the blood of COVID-19 patients." (PMID 33527083, 2021). "Inflammasome-derived products such as Caspase-1 p20 and IL-18 in the sera correlated with the markers of COVID-19 severity, including IL-6 and LDH." (PMID 34960782, 2021). "When plasma IL-6 and gp96 were jointly predicted, the ROC curve integral of severe COVID‐19 was increased to 0.819, which was a good predictor of severe COVID-19." (PMID 34817280, 2021). "Increasing MDSCs during the early stages of COVID-19 were correlated with IL-1β, IL-6, IL-8, and TNF-α plasma levels, particularly in patients who required intensive care treatments, suggesting new therapeutic options geared toward MDSCs42." (PMID 34341347, 2021). "Our data confirmed previous results that neutrophil-to-lymphocyte ratio and circulating levels of IL-6 represent prominent biomarker for the prediction of disease severity and survival of COVID-19." (PMID 33584733, 2021). "As far as COVID-19 is concerned, evidences have accumulated supporting the concept that IL-6 plays a major role in the cytokine storm." (PMID 33981314, 2021). "Some inflammatory biomarkers, including IL-6, IL-1, and galectin-3 (Gal-3), have been proposed as a link between COVID-19 and AD." (PMID 33673697, 2021). "It is important to underline that TNF α and IL6, which are increased in IBD patients, have been also associated with severe forms of COVID-19." (PMID 34572185, 2021). "Pro-inflammatory cytokine interleukin-6 (IL-6) and C-reactive protein (CRP) are biomarkers associated with the COVID-19 progression, severity and mortality." (PMID 34765620, 2021). "Despite widespread decreases in most amino acids, circulating levels of kynurenine, a tryptophan catabolite (and other kynurenine pathway intermediates) were confirmed to be significantly increased in COVID-19 patients as a function of IL-6 levels." (PMID 34571942, 2021). "Accordingly, we recommend that the suitable timing to administer TCZ in patients with COVID-19 is in the early stage of the cytokine storm and, in particular, when the baseline level of IL-6 is less than 100 pg/ml." (PMID 33937333, 2021). "We have identified that elevated levels of IL-6, IL-8, and MIP-1β during SARS-CoV-2 acute infection are associated with severe COVID-19, defined by the development of ARDS or the need of invasive mechanical ventilation or ICU admission." (PMID 34835384, 2021). "The level of IL-6 increased with the severity of infection in patients with COVID-19, which was indicated by SCSS." (PMID 33746945, 2021). "Even though there is no direct clinical data that show Vitamin D alone can effectively treat respiratory viral infection such as COVID-19, there are multiple studies showing a relationship between vitamin D and inflammatory markers such as IL-6 and TNF-alpha." (PMID 34698139, 2021).
COVID-19 (continued). "To date, numerous trials have been approved and/or started to evaluate the effectiveness of anti-IL-6 in patients with severe manifestations of COVID-19." (PMID 33669218, 2021). "The mean IL-6 serum level was nearly 100 times higher in patients with CAR T cell-induced CRS compared with patients with COVID-19." (PMID 34199506, 2021). "IL-6 can result in lymphopenia; where COVID-19 patients typically have significantly altered lymphocyte subsets." (PMID 34199761, 2021). "In patients with COVID-19, IL-6 inhibitors have shown to be beneficial in reducing mortality, particularly in severely ill cases." (PMID 34872623, 2021). "On the other hand, a significant positive correlation between KIR 2DS4 expressed in the CD56brightCD16neg/dim cell subset and both the IFN-γ and IL6 levels (p = 0.002 and p = 0.008, respectively) was found in COVID-19 patients." (PMID 35062250, 2021). "The cytokine profiles in severe COVID-19 patients are similar to those in cytokine release syndromes, with increased production of cytokines such as interleukin (IL)-6, IL-7 and tumor necrosis factor (TNF) and also CXC-chemokine ligand 10 (CXCL10)." (PMID 33995267, 2021). "Hyperinflammation in COVID-19, also described as a cytokine storm, is characterized by increased proinflammatory cytokines, such as IL-6 and TNF-α." (PMID 34744508, 2021). "Analysis revealed a stronger positive correlation between the serum values of IL-33 and TNF-α (p = 0.000), IL-1β (p = 0.000), IL-6 (p = 0.000), IL-12 (p = 0.000), and IL-23 (p = 0.000) in COVID-19 patients with severe disease." (PMID 34917631, 2021). "Most patients with severe COVID-19 exhibited large amounts of pro-inflammatory cytokines and chemokines, such as IL-2, IL-6, IL-7, TNF-α, granulocyte colony stimulating factor (GCSF), CXC-chemokine ligand 10 (CXCL10), CC-chemokine ligand 2 (CCL2), and CCL3." (PMID 33987176, 2021). "Furthermore, reduced GH levels are associated with an increased pro-inflammatory function of macrophages and elevated secretion of inflammatory cytokines like TNFα and IL6, and therefore could promote the inflammatory syndrome that is associated with severe COVID-19." (PMID 33824998, 2021). "Based on these observations of HIS, various types of anti-cytokine therapies were evaluated in COVID-19 patients, including anti-interleukin-6 (IL-6), anti-interleukin-1 (IL-1) and anti-granulocyte-monocyte colony-stimulating factor (GM-CSF)." (PMID 34937556, 2021). "High levels of proinflammatory cytokines, particularly IL-6, IL-8 and IL-1β, were found in the BALFs of severe COVID-19 patients." (PMID 33912590, 2021). "A hyper-inflammatory response, which presents as a cytokine storm, exacerbates COVID-19 severity with high levels of serum IL-6, IL-8, TNF-α, and IL-1β, thus indicating low chances of patient survival." (PMID 33800947, 2021). "The calculated mean IL-6 level in COVID-19 patients was 36.7 pg/mL (ranging between 6.5 and 357.2 pg/mL)." (PMID 34199506, 2021). "Clinical data have shown that COVID-19 patients, especially severe patients, experienced significantly elevated systemic levels of IL-6 compared to healthy controls." (PMID 34764867, 2021). "ROC curve analysis revealed that areas under the curve of lymphocyte counts (LYM), C-reaction protein (CRP), erythrocyte sedimentation rate (ESR), interleukin-6 (IL-6), and SP-D for severe COVID-19 were 0.719, 0.833, 0.817, 0.837, and 0.922, respectively." (PMID 34344306, 2021). "Classification and Regression Tree (CART) further indicated that IL-6 discriminated controls and COVID-19 patients, whilst IL-8 defined disease severity." (PMID 34675240, 2021). "Immune dysregulation in patients with severe COVID-19 is driven by either overproduction of proinflammatory cytokines downstream of IL-6 or CD4 lymphopenia-induced lymphocytic dysregulation." (PMID 34001144, 2021). "In our COVID-19 infected patient group we have documented elevated IL-6 levels, upper the normal limits, in almost all the patients." (PMID 33658032, 2021).
COVID-19 (continued). "Systemic cytokine profiles in patients with COVID-19 are similar to those observed in cytokine release syndromes often driven by macrophages, including high levels of circulating IL-6, IL-17, TNFα, CCL2, and CXCL10." (PMID 33643308, 2021). "In a meta-analysis, IL-6 levels were reported to be >12-fold elevated in COVID-19 related respiratory distress." (PMID 34111164, 2021). "In COVID-19, IL-6 becomes upregulated (TLR-8-induced in neutrophils, C5a-induced in monocytes/macrophages), enhancing neutrophil superoxide production, and delaying apoptosis." (PMID 34485339, 2021). "Interleukin-6 and several other cytokines are pivotal to the immunopathogenesis of cytokine storm, and IL-6 elevations have been reported in some severe COVID-19 studies." (PMID 34501738, 2021). "Recent studies highlight the importance of biomarkers like D-Dimer, anticardiolipin IgG autoantibody, C-reactive protein, and interleukin-6 in the prediction of COVID-19 patients’ clinical decline." (PMID 34070021, 2021). "In this respect, the mild A COVID-19 subgroup showed significant positive correlations between all interferons and between IL-6 and all interferons." (PMID 33717074, 2021). "The distribution of observed IL-6 levels during the ongoing COVID-19 pandemic (mean = 68 pg/mL) is thus shifted towards higher levels compared to the IL-6 levels from earlier years (mean = 11 pg/mL)." (PMID 33723251, 2021). "Fatal COVID-19 is associated with acute respiratory distress syndrome (ARDS) and elevated markers of systemic inflammation including IL-6 and C-reactive protein (CRP), often accompanied by peripheral blood neutrophilia and lymphopenia." (PMID 33692097, 2021). "IL-2R (p = 0.01) and IL-6 (p = 0.001) were found to have relationships with inferior prognosis in patients with COVID-19." (PMID 34970527, 2021). "Severe patients have significantly elevated levels, and one study found high levels of IL-1β persistent in COVID-19 patients up to 4 weeks after symptom onset—similar to IL-6." (PMID 34575258, 2021). "Although the profile of inflammatory markers is highly variable between patients, a general phenotype of severe COVID-19 is characterized by elevated IL-6, IL-8, IL-10, TNF-alpha, CCL2, CCL3, and CXCL8." (PMID 34830356, 2021). "Longitudinal analysis showed higher concentrations of IL-6 and MCP-1 associated with higher risk of mortality in COVID-19 hospitalized patients." (PMID 34539631, 2021). "A large study that enrolled 1500 hospitalized COVID-19 patients, demonstrated that serum levels of IL-6, IL-8, and TNF-α were elevated at the time of admission and correlated with mortality." (PMID 34945111, 2021). "One small study showed lower plasma CRP and IL-6 levels and lower mortality in COVID-19 patients who were treated with siltuximab." (PMID 34578460, 2021). "At the same time, considerably lower and sometimes normal levels of IL-6 have been found in some patients during the crucial phase of COVID-19." (PMID 34299201, 2021). "As a major driver in triggering CRS in patients with COVID-19, interleukin-6 (IL-6) appears to be a promising target for therapeutics." (PMID 33628091, 2021). "The occurrence of affective and psychotic symptoms in the context of COVID-19 can be driven by elevated IL-6 levels which interfere with serotonergic and glutamatergic neurotransmission in the brain." (PMID 34650454, 2021). "Similar in other inflammatory diseases, IL-6 stimulates the release of NETs throughout the body of COVID-19 patients." (PMID 34737734, 2021). "Many inflammatory biomarkers, such as interleukin (IL)-2, IL-6, IL-10 and tumor necrosis factor, were found higher in COVID-19 patients with severe disease, compared with those with mild or moderate disease." (PMID 34640618, 2021). "In patients with severe COVID-19, a decrease in lymphocytes count was negatively correlated to the serum inflammatory cytokines levels (IL-6, TNF)." (PMID 34952570, 2021).
COVID-19 (continued). "The role of IL-6 inhibition in reducing COVID-19 severity and mortality, however, remains controversial because several large-scale, multi-center observations and randomized clinical trials show minimal benefits." (PMID 34001244, 2021). "A study of 140 COVID-19 patients found elevated levels of IL-6 in 95, CRP in 91 and PCT in 8 patients, at admission." (PMID 33727641, 2021). "Anti-inflammatory treatments targeting IL-6 and IL-1, as well as hemoperfusion techniques, have shown evidence of utility in severe COVID-19, suggesting an exacerbated inflammatory response partly mediates severity." (PMID 34960684, 2021). "In previous publications, race, biological sex, and IL-6 level were important predictors of mortality in COVID-19 patients." (PMID 34123422, 2021). "Amygdalin is a candidate compound for COVID-19 treatment by regulating IL6, SRC, MAPK1 EGFR and VEGFA to involve in PI3K-Akt signaling pathway, VEGF signaling pathway and MAPK signaling pathway." (PMID 34908920, 2021). "The high levels of IL-6 observed in this study are consistent with those reported in severe COVID-19 patients in a previous study." (PMID 34285712, 2021). "It has been observed that LMWH improves the coagulation dysfunction of COVID-19 patients and exerts anti-inflammatory effects by reducing IL-6 and increasing lymphocyte %." (PMID 35062238, 2021). "Cytokine release syndrome (CRS) is a key feature of severe COVID-19 and increased serum level of IL-6 correlates with ARDS and adverse clinical outcomes." (PMID 33757410, 2021). "Severe infections with SARS-CoV-2 are often accompanied by a massive cytokine storm with IL-6 as the driver of inflammation present in the lungs and serum of COVID-19 patients." (PMID 34122407, 2021). "Patients with moderate COVID-19 disease had elevated levels of TNFα and IL-6, and in severe COVID-19 cases the production of IL-6 and TNF-α and other cytokines was profoundly increased." (PMID 33465050, 2021). "In COVID-19 patients, the hyperproduction of proinflammatory cytokines, such as IL-1, IL-6, IL-12, IFN-γ, and TNF-α, helps determine the severity of the disease." (PMID 34635175, 2021). "A study done in Italy found that three critically ill patients with COVID-19 developed candidemia after treatment with Tocilizumab, an IL-6 inhibitor." (PMID 34940403, 2021). "COVID-19 patients have increased levels of pro-inflammatory effector cytokines, such as tumor necrosis factor alpha (TNFα), interleukin (IL)-1B, and IL-6, as well as chemokines, such as CCL2 and CXCL10, especially in those who are critically ill." (PMID 33730024, 2021). "Although COVID-19 patients have decreased CD4+ and CD8+ T cells, increased IL-6 and IL-10 levels, associated with cytokine storm, are linked to disease severity." (PMID 34244584, 2021). "Assess Efficacy of HB-adMSCs to treat COVID-19 patients.Primary endpoints: detect change from baseline in inflammatory markers (IL-6, IL-10, TNF-alpha, C Reactive protein), improving oxygenation, and decreasing time to return to room air (RTRA)." (PMID 33815867, 2021). "The DBN model yielded notable dependencies between TNF and IL-6, which support its robustness and generalizability since the analysis has identified both as predictors for monitoring COVID-19 patients." (PMID 35054223, 2021). "Another school of thought is based on the observation that the median IL-6 levels are relatively low in patients with COVID-19, suggesting that the disease as a hypoinflammatory vasculopathy, rather than by hypercytokinemia." (PMID 33557330, 2021). "Our study is the first to report on the role for sMAdCAM in the pathology of and immunity against SARS-CoV-2 as well as on its utility together with IL-6 levels (sMIL index) in serving as an integrative disease progression marker for COVID-19." (PMID 34194420, 2021).